CTLA4 (cytotoxic T-lymphocyte associated protein 4)
Diseases named in the same sentence as CTLA4 in open-access papers (continued):
Sharing a sentence is not in itself a finding about the gene and the disease.
cancer (continued). "Their binding to the T cell co-inhibitory CD28 family receptors, including programmed cell death receptor 1 (PD-1) and cytotoxic T-lymphocyte-associated protein 4 (CTLA-4), results in decreased immune cell activity, allowing cancer cells to escape from immune surveillance." (PMID 34439774, 2021). "The revelation that immune checkpoint inhibition targeting cytotoxic T-lymphocyte associated protein-4 (CTLA-4) or programmed cell death protein (PD-1) could prolong survival in a range of malignancies launched a revolution in the immunotherapy space." (PMID 34944850, 2021). "In our research, we found that the deletion of Casp8 in NK cells resulted in the dysfunction of the NK cells, but it also increased the expression of PD‐1 and CTLA‐4 on NK cytomembranes, which has been reported to be associated with poor prognosis in various cancers." (PMID 33934451, 2021). "In recent decades, immune checkpoint inhibitors (ICIs) targeting programmed cell death protein 1 (PD-1), programmed death-ligand 1 (PD-L1), and cytotoxic T lymphocyte-associated protein 4 (CTLA-4) have revolutionized the treatment landscape for patients with advanced cancer." (PMID 34604047, 2021). "A recent remarkable success of treating advanced cancer with immune check-point inhibitors (ICIs) highlight important roles that programmed cell death protein-1 (PD-1) and cytotoxic T lymphocyte-associated protein-4 (CTLA-4) play in the suppression of anti-cancer immune responses." (PMID 33665689, 2021). "Currently, with an unprecedented sustained and stable antitumor response, immunotherapy cytotoxic T lymphocyte-associated antigen 4 (CTLA4) or programmed cell death protein 1 (PD-1)/PD-1 ligand 1 (PD-L1) has demonstrated remarkable efficacy against various types of cancer." (PMID 33968730, 2021). "Monoclonal antibodies can be considered a type of protein-based drug where the antibodies are engineered to target cell death (programmed death receptor 1, PD-1) or cytotoxic T-lymphocyte-associated antigen 4 (CTLA-4) and are commercialized to be used in the clinic to treat different cancers." (PMID 33503889, 2021). "These strategies consist of neutralizing antibodies against negative immune checkpoints as Cytotoxic T-Lymphocyte Associated Protein 4 (CTLA-4), Programmed Cell Death 1 (PD-1), and PD-1 Ligand-1 (PD-L1), thereby impeding the ability of cancer cells to evade the immune surveillance program." (PMID 34067257, 2021). "A novel approach to treat various cancers combines ERV re-activation using histone deacetylase inhibitors (HDACi) in combination with immune checkpoint inhibitors targeting PD-1 or Cytotoxic T-Lymphocyte Associated Protein 4 (CTLA-4)." (PMID 33669629, 2021). "Checkpoint inhibitors have taken center stage in cancer immunotherapy research, since they block signaling through immune inhibitory molecules, especially programmed cell death protein 1 (PD-1) and cytotoxic T-lymphocyte associated protein 4 (CTLA4)." (PMID 33679808, 2021). "Currently, the most relevant immunological checkpoints in cancer immunotherapy are cytotoxic T- lymphocyte-associated protein 4 (CTLA-4) and programmed cell death protein 1 (PD-1) expressed in T lymphocytes and programmed cell death ligand 1 (PD-L1) expressed on the cancer surface." (PMID 34823601, 2021). "In the past few years, cancer immunotherapy has made leaps and bounds due to a better understanding of immune surveillance and usage of immune checkpoints including cytotoxic T-lymphocyte-associated protein 4 (CTLA-4) and programmed cell death protein 1 (PD-1)." (PMID 34884721, 2021). "Another immune checkpoint pathway that could negatively regulate T-cell anti-tumor function in the setting of cancer is cytotoxic T-lymphocyte–associated antigen 4 (CTLA-4) and macrophage Clever-1." (PMID 34803925, 2021).
cancer (continued). "Cancers may express checkpoint molecules such as cytotoxic T-lymphocyte-associated protein 4 (CTLA-4) and programmed cell death protein ligand 1 (PD-L1), which negatively regulates the activation of T cells." (PMID 34447390, 2021). "At the latest since the Nobel Prize was presented to Tasuku Honjo and James P. Allison in 2018, immune checkpoint inhibitors, including programmed cell death protein-1 (PD-1) or cytotoxic T-lymphocyte-associated Protein 4 (CTLA-4), have been ubiquitously present in the treatment of cancer." (PMID 35155273, 2021). "The use of programmed death 1 (PD-1)/programmed death ligand 1 (PD-L1) or cytotoxic T-lymphocyte-associated antigen 4 (CTLA-4) immune checkpoint inhibitors (ICIs) has become a standard in the treatment of various cancers, including NSCLC, with significant clinical benefits." (PMID 33673461, 2021). "Immune checkpoint inhibitors (ICIs), such as anti-cytotoxic T lymphocyte-associated antigen 4 (anti-CTLA-4), anti-programmed cell death 1 (anti-PD-1), and anti-programmed death-ligand 1 (anti-PD-L1), have revolutionized the management of malignant tumors, especially those at advanced stages." (PMID 34885219, 2021). "In particular, immunecheckpoint inhibition (ICI) strategies targeting the programmed cell death protein 1 (PD-1), programmed cell death protein ligand 1 (PD-L1), and cytotoxic T-lymphocyte-associated protein 4 (CTLA-4) are approved for a large number of different cancers." (PMID 34360781, 2021). "Understanding of the importance of this role ultimately led to the discovery that tumors utilize critical immune checkpoint molecules such as programmed death ligand 1 (PD-L1) and cytotoxic T lymphocyte associated protein 4 (CTLA-4) as a means to prevent immune activation towards cancer cells." (PMID 34778089, 2021). "However, the association of CD36 expression with CD274 (PDL-1) and CTLA4 was inconsistent among different cancer types." (PMID 34234847, 2021). "Immune checkpoint inhibitors (ICIs) targeting the cytotoxic T-lymphocyte-associated protein-4 (CTLA-4) and programed cell death protein 1 (PD-1) or its ligand PD-L1 have increased the survival and cure rates for patients with many cancer types in various disease settings." (PMID 33950415, 2021). "It remains to be seen whether anti-CTLA4 treatment may confer a secondary cancer risk in the very long term, and whether type 2 inflammation has a role in that regard." (PMID 34235145, 2021). "Moreover, CD36 expression presented a disease-specific association with CD274 (PDL-1) and CTLA4 among different cancer types." (PMID 34234847, 2021). "Immune checkpoint inhibitors (ICIs), such as cytotoxic T-lymphocyte-associated protein 4 (CTLA-4), programmed cell death protein-1 (PD-1), and programmed death ligand 1 (PD-L1) inhibitors, have been widely used as a standard cancer treatment during recent years." (PMID 32847555, 2020). "Based on previous research results, BTNs play important roles in cancer immunity, which might serve as new targets or therapeutic strategies and may be effective for anti–PD-1 or anti–cytotoxic T-lymphocyte-associated protein 4–unresponsive patients." (PMID 32695099, 2020). "Since 2010, cancer immunotherapy drugs including CTLA4 (cytotoxic T-lymphocyte-associated protein 4) inhibitors, PD-1 (programmed cell death protein 1) inhibitors, PD-L1 (programmed cell death ligand 1) inhibitors, and CAR (chimeric antigen receptor)-T cell therapy have received a lot of attention." (PMID 33028046, 2020). "Additionally, cancer immunotherapies which inhibit immune checkpoints (ICs) such as programmed cell death protein 1/programmed cell death 1 ligand 1 (PD1/PD-L1) and cytotoxic T-lymphocyte-associated protein 4 (CTLA4) have become landmarks in cancer treatment." (PMID 33469537, 2020).
cancer (continued). "Cancer cells exploit the “immune checkpoint” function to evade the immune system by expression of programmed cell death-1 (PD-1) or anti–cytotoxic T-lymphocyte-associated antigen-4 (CTLA-4) resulting in increased apoptosis of T cells." (PMID 32670880, 2020). "Immune checkpoint blockade (ICB) with antibodies inhibiting cytotoxic T lymphocyte-associated protein-4 (CTLA-4) and programmed cell death protein-1 (PD-1) (or its ligand (PD-L1)) can stimulate immune responses against cancer and have revolutionized the treatment of tumors." (PMID 32430031, 2020). "Immunotherapy drugs targeting the programmed cell death protein-1 (PD-1), programmed cell death ligand-1 (PD-L1), or cytotoxic T-lymphocyte-associated antigen 4 (CTLA-4) block the cancer-derived inhibitory signal on effector T-cells and remove residual cancer cells." (PMID 32722386, 2020). "Based on that, it may be assumed that CTLA-4c.-319*T allele is associated with higher expression of CTLA-4, and therefore, may increase a risk of cancer development and progression." (PMID 33519815, 2020). "Most of the current forms of cancer immunotherapy seek to target molecules on cytotoxic T cells such as cytotoxic T-lymphocyte-associated protein 4 or programmed cell death protein 1, aiming to remove inhibition and hence, boost activation of such antitumor effector cells." (PMID 32699181, 2020). "While antibodies that block immune checkpoint proteins, including cytotoxic T-lymphocyte associated protein 4 (CTLA4) and programmed cell death protein 1 (PD-1), have been approved to treat a variety of cancers, the majority of cancer patients see little benefits from these treatments." (PMID 32039830, 2020). "Treatment with antibodies that block inhibitory receptors, such as cytotoxic T lymphocyte associated protein 4 (CTLA-4), programmed death receptor 1 (PD-1), or its ligand PD-L1, can lead to durable complete responses in some patients depending on the cancer type." (PMID 33163002, 2020). "The recent development of cancer immunotherapies using immune checkpoint inhibitors (ICIs) targeting cytotoxic T-lymphocyte-associated protein-4 (CTLA-4) and anti-programmed cell death protein-1 (PD-1) has dramatically changed the landscape of cancer therapy and was awarded the Nobel Prize in 2018." (PMID 32218257, 2020). "ICIs are an important method of cancer immunotherapy and are aimed at blocking several targets that interfere with the proliferation of T-lymphocytes, such as cytotoxic T-lymphocyte-associated protein 4 (CTLA-4), programmed cell death 1 (PD-1), programmed cell death ligand 1 (PD-L1)." (PMID 33348704, 2020). "Over the past 5 years, immunotherapy represented by immune checkpoint inhibitors (ICIs) targeting programmed death 1 (PD-1), programmed death ligand-1 (PD-L1) and cytotoxic T lymphocyte-associated antigen-4 (CTLA-4) has become an important milestone in cancer treatment." (PMID 32968172, 2020). "Senescent T cells exhibit abnormal phenotypes, including downregulation of CD27, CD28, and upregulation of CD57, killer cell lectin-like receptor subfamily G, Tim-3, Tight, and cytotoxic T-lymphocyte-associated protein 4, which are tightly related to malignant tumors." (PMID 33168037, 2020). "Additionally, neoantigens produced from cancer somatic mutations are positively associated with response to anti-PD-1 or anti-CTLA-4 treatment." (PMID 31811337, 2020). "In this article, immunotherapy is used exclusively as a term for all cancer therapies based on the specific immune checkpoint inhibitors (ICIs) cytotoxic T-lymphocyte-associated protein 4 (CTLA-4) and programmed cell death protein 1/programmed death-ligand 1 (PD-1/PD-L1)." (PMID 32813113, 2020). "The associations between CTLA-4 polymorphisms and cancer were studied extensively." (PMID 33519815, 2020).
cancer (continued). "Meanwhile, irAEs induced by PD-1 inhibitors predict a better clinical response by patients with cancer, but the association between irAEs and survival in patients undergoing anti-CTLA-4 therapy remains controversial, demanding larger size of studies in the future." (PMID 32306958, 2020). "Nivolumab or pembrolizumab (targeting programmed death 1 [PD-1] checkpoint monoclonal antibody) and ipilimumab (targeting cytotoxic T-lymphocyte-associated antigen 4 [CTLA-4] checkpoint monoclonal antibody) have become standard immune therapy for patients with advanced cancers." (PMID 31754400, 2019). "Immune checkpoint inhibitors (ICIs), including programmed death receptor-1 (PD-1)/ligand (PD-L1) and cytotoxic T-lymphocyte-associated antigen-4 (CTLA-4) monoclonal antibody, have been approved for the treatment of multiple advanced malignant tumors, on account of its ideal antitumor activity." (PMID 31874675, 2019). "Immune checkpoint inhibitors (ICPIs) such as ipilimumab, a CTLA-4 inhibitor, and nivolumab, a PD-1 inhibitor, are more widely used to treat various types of cancers, but they can also be associated with immune-related adverse reactions (irAEs) including enterocolitis, hepatitis, or skin rash." (PMID 30777137, 2019). "Cytotoxic T-lymphocyte-associated protein 4 (CTLA-4) and programmed cell death protein 1 (PD-1), both inhibitory checkpoints commonly seen on activated T-cells have been found to be the most reliable targets for the treatment of cancer." (PMID 31196207, 2019). "Among the molecules that impact the interactions between cancer and immune cells, PD-L1 (programmed death-ligand 1) and CTLA-4 (cytotoxic T-lymphocyte-associated protein 4) are well-known to modulate the immune system and play important roles in cancer development." (PMID 31703738, 2019). "Studying the TME across many cancers has identified upregulation of immune checkpoint co-signaling proteins such as cytotoxic T-lymphocyte-associated antigen 4 (CTLA-4) and programmed death-1 (PD-1), which effectively act as brakes on antitumor immune responses." (PMID 31022866, 2019). "Among them, immune checkpoint blockade with antibodies that target cytotoxic T lymphocyte-associated antigen 4 (CTLA-4) and the programmed cell death protein 1 pathway (PD-1/PD-L1) is demonstrating dramatic antitumor effects in subsets of patients in a variety of cancer types." (PMID 31150505, 2019). "Moreover, upregulation and overexpression of immune checkpoints CTLA-4 (cytotoxic T lymphocyte associated antigen 4) or PD-L1 (programmed cell death protein ligand 1) on cancer cells induces T cell anergy and maintains Treg induced immunosuppression." (PMID 31024545, 2019). "The seminal discovery of enhanced antitumor immunity by blockade of the cytotoxic T-lymphocyte-associated protein 4 (CTLA-4) by Allison and colleagues in 1996 has led to the rapid development and uptake of immunotherapy as standard of care for many types of cancer." (PMID 30717307, 2019). "Cancer cells can evade immune surveillance through the molecular interactions of immune checkpoint proteins, including programmed death 1 (PD-1), PD-L1, and cytotoxic T lymphocyte-associated antigen 4 (CTLA-4)." (PMID 30917623, 2019). "Furthermore, we explored the correlation between ARID1A mutations and immune checkpoint blockade therapy response using three cancer immunotherapy (anti-PD-1/PD-L1/CTLA-4) response-associated cohorts (Allen cohort, Hugo cohort, and Samstein cohort)." (PMID 31277418, 2019). "Whether abatacept treatment will decrease the risk to develop cancer in CTLA-4 insufficiency remains to be proven, as the substitution of CTLA4-Fc ameliorates the dysregulated immune response." (PMID 30250467, 2018). "In addition, comparing the risk of cancer between the general population and affected CTLA4 mutations carriers, affected CTLA4 mutation carriers had a higher cancer rate per year." (PMID 30250467, 2018).
cancer (continued). "Cancer predisposition in CTLA-4 insufficiency appears as a result of immune activation with chronic inflammation, failure to control oncogenic viruses or neoplastic cells by immunological means, plus an intrinsic T cell impairment due to the underlying genetic defect." (PMID 30250467, 2018). "Indeed, a survey of 131 affected CTLA4 mutation carriers shows a cancer prevalence of 12.9%, mainly lymphoma, gastric adenocarcinoma and metastatic melanoma." (PMID 30443258, 2018). "The “Checkpoint blockade” that utilizes mAbs specific to cytotoxic T lymphocyte-associated antigen 4 (CTLA-4) and the programmed cell death protein 1 pathway (PD-1/PD-L1), is arising as a newer strategy used to fight cancer and one of the most promising immunotherapies." (PMID 29527212, 2018). "While the clinical breakthrough of immune checkpoint inhibitors such as anti-programmed death-1 (PD-1) or cytotoxic T-lymphocyte-associated protein 4 (CTLA-4) in certain cancers has fueled optimism in immunotherapy, the efficacy is limited to a small subset of patients." (PMID 30400835, 2018). "A previous study has shown that the anti-cancer efficacy and immunostimulatory effect of cytotoxic T-lymphocyte-associated protein 4 (CTLA-4) blockade, an immune checkpoint blockade, rely upon different Bacteroides species, such as the Bacteroides thetaiotaomicron and B. fragilis." (PMID 29474889, 2018). "However, the relationship of CTLA-4 rs733618 T>C polymorphism with the development of cancer was conflicting." (PMID 29100337, 2017). "Dr. Mellman began by presenting an overview of the “cancer immunity cycle”, highlighting cytotoxic T lymphocyte-associated protein 4 (CTLA-4) and anti-PD-1/programmed death-ligand 1 (PD-L1) as negative regulators of the T cell response that are necessary to maintain immune homeostasis." (PMID 28716068, 2017). "These agents inhibit negative regulatory components of the immune response, such as the cytotoxic T lymphocytes-associated antigen 4 (CTLA-4) and the programmed cell death protein-1 and its ligand (PD-1/PD-L1), which lead to enhanced T cell action against the cancer cells." (PMID 28228726, 2017). "A major recent advance in the treatment of human cancer involves the therapeutic targeting of immune response ‘checkpoints’ via antibodies that interfere with cytotoxic T lymphocyte-associated antigen (CTLA)-4 and programmed cell death (PD)-1 receptors and their ligands (reviewed in ref.44)." (PMID 29176694, 2017). "Moreover, T cell checkpoint blockade therapy with antibodies targeting cytotoxic T-lymphocyte associated protein 4 (CTLA-4) has improved outcomes in cancer patients." (PMID 28416753, 2017). "Recent breakthrough developments in cancer immunotherapy include checkpoint blockade therapy targeting cytotoxic T-lymphocyte-associated antigen 4 (CTLA-4) and programmed death receptor-1 (PD-1) as well as adoptive transfer of engineered T cells or chimeric antigen receptor (CAR) T cells." (PMID 28031824, 2016). "Despite the complexity of cancer immunoediting, growing evidences suggest that the co-inhibitory receptors, such as cytotoxic T lymphocyte-associated antigen-4 (CTLA-4) and programmed death 1 (PD-1), play a crucial role in cancer immunoediting, especially in the equilibrium and escape stages." (PMID 26114883, 2015). "Therefore, this study was designed to investigate the associations between five CTLA4 SNPs (rs733618 C/T, rs4553808 A/G, rs5742909 C/T, rs231775 A/G, and rs3087243 G/A) and malignancy in Chinese renal transplantation recipients." (PMID 25667935, 2015). "However, based on case reports, irAE occurrence seems to be associated with clinical response to CTLA-4 blocking: 60 % of the patients presenting with irAEs experienced clinical remission (partial or complete) or at least cancer stabilization." (PMID 26337719, 2015).